CRP (C-reactive protein)
Diseases named in the same sentence as CRP in open-access papers (continued):
Sharing a sentence is not in itself a finding about the gene and the disease.
polyarthritis (35 papers, 2006 to 2026). "The possibility of ARF was considered by the rheumatology team when consulted, given that the patient had two major criteria (carditis and polyarthritis) and two minor criteria (elevated CRP and fever) according to the modified Jones diagnostic criteria for acute ARF." (PMID 40724633, 2025). "A diagnosis of ARF was arrived at about three weeks after her first presentation, when she manifested two major criteria (carditis and polyarthritis) and two minor criteria (elevated CRP and fever)." (PMID 40724633, 2025). "We treated a patient with long-term hemodialysis who presented with polyarthritis, elevated CRP, and systemic inflammatory symptoms such as fever, in the context of dialysis-related amyloid deposition characteristic of the shoulder and femoral head." (PMID 40571902, 2025). "Poor prognostic factors include polyarthritis, joint damage, high sedimentation rate or CRP, and clinically relevant extra-articular features." (PMID 38217738, 2024). "An 80-year-old woman was diagnosed with RA in 2010 based on polyarthritis, high serum C-reactive protein levels, positive for anti-cyclic citrullinated peptide (CCP) antibody, and rheumatoid factor (RF)." (PMID 34660652, 2021). "On multivariable analysis, independent correlations with lack of achievement of ID were identified for the disease categories of systemic arthritis, enthesitis-related arthritis (ERA) and polyarthritis and C-reactive protein (CRP) > 1.4 mg/dl." (PMID 31345226, 2019). "Patients with systemic arthritis, ERA and polyarthritis with increased CRP were less likely to achieve ID." (PMID 31345226, 2019). "Polyarthritis and increased CRP, whose score was 0.5, assumed a predictive value only when present in association." (PMID 31345226, 2019). "The variables that remained independently associated with lack of attainment of ID in the best-fitted model of logistic regression procedures were systemic arthritis, ERA, polyarthritis and elevated CRP." (PMID 31345226, 2019). "Independent correlations with lack of achievement of ID were identified for the functional categories of systemic arthritis, ERA and polyarthritis (versus oligoarthritis) and a CRP value greater than 1.4 mg/dl." (PMID 31345226, 2019). "A 64-year-old man on hemodialysis for >30 years was admitted because of intermittent fever, polyarthritis, and elevated serum C-reactive protein (CRP) level, which was continuous for 2 years." (PMID 29505515, 2018). "A 64-year-old Japanese man on hemodialysis for over 30 years was admitted to our hospital in 2016 with intermittent fever, polyarthritis, and elevated C-reactive protein (CRP)." (PMID 29505515, 2018). "The CRP concentrations in these two dogs were of similar magnitude as those reported in other studies of immune-meditated polyarthritis." (PMID 28416005, 2017). "When she was 50 years old, polyarthritis developed, and rheumatoid factor and C-reactive protein (CRP) levels were high." (PMID 25216562, 2014). "The CRP was already increased at the first relapses of clinical signs of polyarthritis (day 47–49 and day 61–95) and CRP was persistently high during the periods of clinical signs." (PMID 16987405, 2006). "However, 2 weeks later, the patient experienced polyarthritis with an increased level of CRP (23.16 mg/dL)." (PMID 31577714, 2019). "Thus, a marked increase in CRP were observed on two occasions, related to the reappearence of clinical signs of polyarthritis." (PMID 16987405, 2006). "However, his polyarthritis worsened with an increased level of CRP (23.16 mg/dL)." (PMID 31577714, 2019). "This was in a child considered to have definite ARF based on polyarthritis, fever, prolonged PR interval, elevated ESR and CRP and positive streptococcal serology." (PMID 40675648, 2025). "A 50-year-old man was diagnosed as having RA 4 years ago, on the basis of symmetrical polyarthritis affecting the wrists, elbows and the knees bilaterally, and with positive IgM-RF and high ESR and CRP." (PMID 35611100, 2022).
polyarthritis (continued). "More specifically, bilateral symmetrical polyarthritis of the small joints of the hands, positive anti-citrullinated protein antibodies (ACPA), positive IgM rheumatoid factor (IgM-RF), as well as high CRP and erythrocyte sedimentation rate (ESR)." (PMID 35611100, 2022). "All patients reached clinical remission of polyarthritis and improvements in the erythrocyte sedimentation rate (ESR) and levels of C-reactive protein (CRP) and inflammatory cytokines." (PMID 34781959, 2021). "Given the migratory pattern of joint involvement and weakly positive anti-CCP antibodies with very mildly elevated CRP in an otherwise negative work-up, a working diagnosis of early RA with an atypical migratory polyarthritis presentation was made." (PMID 40709149, 2025). "However, given the presence of one major criterion (polyarthritis) and two minor criteria (prolonged PR interval and elevated ESR and CRP), along with evidence of preceding GAS infection (elevated ASO titer), the diagnosis of ARF was established." (PMID 40970077, 2025). "Polyarthritis should be included in the differential diagnosis for all dogs with increased CRP concentrations, even those without gait‐related clinical signs." (PMID 40864877, 2025). "In this study, all of the four patients received IFX plus methotrexate, and all achieved clinical remission of skin lesions and polyarthritis rapidly, as well as normalization of ESR and CRP and improvements in VAS, PGA, and SF-36, at the first follow-up of 6 months." (PMID 31718710, 2019). "Indeed, polyarthritis was present in all ACPA-positive patients, involving numerous small joints, with a distribution resembling that of RA, along with higher CRP amount and a positive test for rheumatoid factor." (PMID 25997035, 2015). "In one previous prospective study from disease onset, CRP at baseline was found to predict death due to CVD in a cohort comprising patients with polyarthritis rather than RA." (PMID 21843325, 2011). "In cases of lameness, CRP evaluation can facilitate differential diagnosis between immune-mediated or septic polyarthritis and other conditions that do not produce changes in CRP, such as intravertebral disc protrusion as well paraplegia secondary to acute intervertebral disc extrusion." (PMID 36290272, 2022). "In addition, greater C-reactive protein concentration and polyarthritis predicted ACR50, and non-involvement of large joints predicted a good response according to EULAR criteria." (PMID 19815494, 2010). "The levels of RANKL increased significantly more from baseline to follow-up in the polyarthritis-group than in the oligoarthritis-group (p = 0.015), while the changes in OPG, OPG/RANKL ratio and CRP were not significantly different." (PMID 21134287, 2010). "Based on one major (polyarthritis) and three minor criteria (fever, prolonged PR interval, elevated ESR or CRP), along with evidence of a recent GAS infection (elevated ASO titer), the diagnosis of ARF was established according to the 2015 revised Jones criteria." (PMID 40970077, 2025).
pyelonephritis (35 papers, 2009 to 2025). An inflammatory process affecting the kidney. "On the other hand, a meta-analysis evaluating the diagnostic accuracy of CRP in pyelonephritis in children found that with a 20 mg/L cut-off, sensitivity was 94%, and specificity was 39%." (PMID 38542009, 2024). "Thus, as seen in our patient, low CRP levels (especially lower than 2mg/dl) could not exclude acute pyelonephritis, and it was considered that CRP was only one of the ’predictive’ but poor ‘diagnostic’ markers of pyelonephritis." (PMID 25488491, 2014). "Blood tests on admission showed a raised white cell count and raised C-reactive protein level, and subsequent clinical diagnoses were community-acquired pneumonia, pyelonephritis and infective discitis." (PMID 40388325, 2025). "In our cohort, all the patients with clinical symptoms suggestive of pyelonephritis and elevated infection markers (i.e., C-reactive protein) requiring antibiotics were reported as having a UTI." (PMID 40087256, 2025). "Maximum temperature, C-reactive protein (CRP) levels and procalcitonin have been associated with RS, indicating that a severe kidney infection increases the risk of persistent scarring." (PMID 38767678, 2024). "In previously conducted studies, the usefulness of sequential determination of CRP in acute childhood pyelonephritis was evaluated, that later helped clinicians distinguish between CRP levels in upper and lower UTI." (PMID 35915684, 2022). "In febrile children that are seriously ill, CRP < 20 mg/l gives a LR- of 0.10 (95% CI 0.04–0.30, n = 1) for pyelonephritis." (PMID 34565335, 2021). "New studies should investigate the accuracy of CRP for pyelonephritis at lower thresholds (< 10 mg/l or < 5 mg/l) in children with signs suggestive of UTI." (PMID 34565335, 2021). "Other tests oftencarried out to assess the risk of bacterial infection in febrile infants, such asthe white blood cell count and the reactive C-reactive protein (CRP) test are ofquestionable value for a presumptive diagnosis of pyelonephritis." (PMID 29796576, 2018). "Those with fever, high C-reactive protein (CRP) level (more than 3 mg/L) or ultrasonographic evidence of pyelonephritis were considered as having urosepsis." (PMID 29183356, 2017). "The tubular injury marker, the α1-microglobulin/creatinine ratio, has a high specificity and sensitivity in distinguishing pyelonephritis from cystitis and is positively correlated with baseline C-reactive protein (CRP) levels." (PMID 23522152, 2013). "In UTIs, evidence for the utility of PCT comes primarily from the pediatric literature, where it has a similar sensitivity but superior specificity compared to CRP for the prediction of pyelonephritis in children with febrile UTIs." (PMID 21936959, 2011). "If there is the involvement of kidneys, serum creatinine and CRP (>100 mg/L is consistent with pyelonephritis) may be raised." (PMID 39896133, 2024). "For CRP, to diagnose pyelonephritis, the sensitivity was 64% and specificity was 68%." (PMID 19707519, 2009). "Regarding lab results between two groups, we found that Abnormal urine analysis, elevated serum C-reactive protein (CRP), higher leukocyte counts, and elevated Serum NGAL levels are significantly more prevalent in the pyelonephritis group with P-value < 0.001." (PMID 40467696, 2025). "While current biomarkers like CRP, PCT, and erythrocyte sedimentation rate are extensively utilized in diagnosing and monitoring pyelonephritis, their effectiveness remains debated due to variable sensitivity and specificity values." (PMID 38611690, 2024). "On top of that, readily available serum markers CRP and PCT are often used to prognosticate pyelonephritis in children with UTI." (PMID 35359908, 2022). "Systemic inflammatory markers such as WBCc, ANC, CRP and PCT offer little additional value for cystitis, whereas for pyelonephritis, CRP < 20 mg/l is useful for ruling out and PCT ≥ 2 ng/ml for ruling in." (PMID 34565335, 2021).
pyelonephritis (continued). "Both PCT and CRP can be used for upper and lower urinary tract infection differentiation, but PCT has higher sensitivity and specificity in predicting pyelonephritis than CRP." (PMID 24886302, 2014). "However, the pyelonephritis group exhibited statistically significant differences in Serum NGAL levels, abnormal urine analysis findings, total leukocyte count, and serum C-reactive protein (CRP) levels, with p-values less than 0.001." (PMID 40467696, 2025). "On the contrary, serum CRP, procalcitonin, and presepsin were not significantly different between the pyelonephritis and the nonpyelonephritis groups." (PMID 37259055, 2023). "According to participants, the C-reactive protein (CRP) point-of-care test seemed useful to rule out pyelonephritis, but less so for cystitis." (PMID 35879106, 2022). "Systemic inflammatory markers, such as CRP and PCT offer little added value for cystitis (AUC 0.75 and 0.71), whereas in children with signs suggestive of UTI, CRP < 20 mg/l might be useful for ruling out and PCT ≥2 ng/ml for ruling in pyelonephritis." (PMID 34565335, 2021). "Her urine analysis and sterile culture are not supportive of pyelonephritis, but high CRP and swollen allograft during imaging makes it a possibility." (PMID 30170627, 2018). "In summary, our study described that lower UTIs caused by M. morganii with no specific clinical manifestations had normal or slightly elevated leukocyte counts and PCT levels, and normal CRP levels, but pyelonephriti may accompany with fever symptom, high level of WBC, CRP, and PCT." (PMID 35349730, 2022). "CRP and PCT have low accuracy for cystitis, but might be useful for pyelonephritis." (PMID 34565335, 2021). "As the distinction between febrile UTI and pyelonephritis was not defined in the protocol, we went through the medical records and made the classification based on the doctors’ description of the patients’ symptoms and CRP value." (PMID 29763434, 2018). "It was also more commonly found among those with a recorded ED diagnosis of UTI (lower UTI, pyelonephritis, urosepsis) but not among those with only symptoms of UTI and was strongly associated with urine flow cytometry results and some blood tests, most notably CRP and platelet counts." (PMID 37310941, 2023).
cardiac arrest (34 papers, 2008 to 2025). Cessation of breathing and/or cardiac function. "The association of C-reactive protein concentrations with neurological outcome was more pronounced in the subgroup of patients with cardiac cause of cardiac arrest with an adjusted odds ratio of 1.45 (95% CI 1.20–1.75)." (PMID 33986392, 2021). "In summary, this study suggests that initial capillary lactate levels and capillary lactate levels measured 10 min after CRP could be associated with the type of cardiac arrest." (PMID 38004038, 2023). "Whether admission C-reactive protein (aCRP) concentrations are associated with neurological outcome after out-of-hospital cardiac arrest (OHCA) is controversial." (PMID 33986392, 2021). "In that single-center trial, Tocilizumab reduced systemic inflammation after cardiac arrest, evidenced by decreased C-reactive protein and leukocyte levels." (PMID 38840141, 2024). "In sum, blood samples were drawn within 60–90 min after cardiac arrest, which precludes substantial impact of cardiac arrest on C-reactive protein concentrations." (PMID 33986392, 2021). "Earlier studies have also reported that elevated concentrations of other inflammatory mediators, i.e., C-reactive protein or procalcitonin, also correlate with patients’ clinical states and predicted poor outcome after cardiac arrest." (PMID 27497949, 2016). "Secondary endpoints included procalcitonin/CRP levels on post-operative day 1, length of hospital stay, and cardiac arrest or death." (PMID 22906145, 2012). "The remaining four were all admitted for cardiac arrest that was later complicated by aspiration pneumonia, fever and rising CRP." (PMID 22613179, 2012). "There are not references in the literature about the correlation of both, PCT and CRP, and mortality after cardiac arrest in children." (PMID 18447945, 2008). "The IMICA trial included comatose patients resuscitated from out-of-hospital cardiac arrest and showed that tocilizumab significantly reduced the systemic inflammatory markers CRP and leukocyte counts as well as markers of myocardial injury such as CKMB and troponin levels." (PMID 39501388, 2024). "The increase in CRP after ROSC is caused by the so-called post-resuscitation syndrome, which is ultimately a systemic inflammatory response, triggered by ischemic processes during cardiac arrest." (PMID 38004576, 2023). "Due to a cardiac arrest, CRP was made and then n‐CPAP ventilation (FiO2 30%) was administered." (PMID 35261118, 2022). "In addition, the post-operative CRP levels were associated with CPB duration, circulatory arrest duration and length of ICU stay (p < 0.05)." (PMID 31417881, 2019). "Our objective was to report the time profile of PCT and CRP levels after paediatric cardiac arrest and to assess if they could be use as markers of immediate survival." (PMID 18447945, 2008). "Additionally, in the conventional CPB group, but not in the beating-heart CPB and off-pump technique groups, CRP markedly increased after surgery, indicating that cardiac arrest/ischemia–reperfusion injury plays a critical role in the changes of the serum CRP levels." (PMID 28930238, 2017). "In cardiac-arrest survivors, NHR showed a higher ROC-AUC of 0.74, outperforming CRP (0.58) and slightly exceeding IL-6 (0.69), indicating better prediction of adverse outcomes." (PMID 41162914, 2025). "According to previous studies, the following biomarkers predict outcome after cardiac arrest and ROSC: interleukin-6, high-sensitivity C-reactive protein, serum neuron-specific enolase concentration, and S-100 protein." (PMID 33833877, 2021). "Factors such as old age, CO exposure time, cardiac arrest, initial neurological abnormalities, GCS, brain imaging abnormalities, and biochemical indicators (e.g., neuron-specific enolase, CRP, lactic acid) are related to DNS following CO poisoning." (PMID 32947848, 2020).
cardiac arrest (continued). "Last, the interval between CRP initiation and ROSC was relatively short in some patients, making it difficult to evaluate whether these patients had a cardiac arrest." (PMID 37768915, 2023). "Compared to her twin, she showed an earlier response to the treatment in about 24 h, however cardiac arrest occurred once more, this time with no resumption from CRP." (PMID 35261118, 2022). "While we are not aware of similar location studies for CRP PoC tests, location problems are common in health care, for example a location of sexual health clinics or the placement of defibrillators for cardiac arrest." (PMID 31527896, 2019). "In all our children, survivors and non-survivors, PCT and CRP levels increased at 12 and 24 hours after cardiac arrest, confirming that both markers are elevated in patients with shock." (PMID 18447945, 2008). "It is noteworthy that C-reactive protein levels do not reflect quality or duration of CPR, but rather the health status of patients prior to cardiac arrest." (PMID 33986392, 2021). "PCT is highly activated by endotoxin, and prior pediatric studies of cardiac arrest and CPB have shown that elevated levels of PCT, but not CRP, are predictive of poor outcome." (PMID 22906145, 2012).